CCR2 (C-C motif chemokine receptor 2)
Diseases named in the same sentence as CCR2 in open-access papers (continued):
Sharing a sentence is not in itself a finding about the gene and the disease.
AIDS (22 papers, 2007 to 2025). A syndrome resulting from the acquired deficiency of cellular immunity caused by the human immunodeficiency virus (HIV). "Blood samples were collected from HIV/AIDS screening centers and analyzed for the presence of CCR2-64I using restriction fragment length polymorphism (RFLP)." (PMID 26300579, 2015). "This suggests that the high frequency of CCR2-64I allele is associated with a slower progression to AIDS." (PMID 26300579, 2015). "We established that a CCR2-64I variant associated with a delay in AIDS progression is carried by some pygmies." (PMID 23217182, 2012). "This study was carried out to identify variants of the CCR2 gene among HIV/AIDS clients as the frequency of these genetic variants in Kenya, particularly in HIV-1 seropositive and/or seronegative high-risk populations, is currently unknown." (PMID 26300579, 2015). "However, despite the high prevalence of HIV in Africa, the CCR2-64I mutation alone is but one possible factor in HIV/AIDS development." (PMID 23880174, 2013). "Herein, we investigate the proportion of the mutated phenotype of the AIDS-related polymorphisms CCR5-Delta32, CCR2-64I, and SDF1-3’A in HIV-infected and uninfected individuals in Luanda, the capital of Angola, a sub-Saharan African country." (PMID 40413451, 2025). "This discrepancy in the scientific literature shows that further studies should be conducted to verify the role of the CCR2-64I mutation in susceptibility to HIV infection, AIDS progression, and/or mortality in people living with HIV in Africa." (PMID 40413451, 2025). "CCR2 variants are associated with a protective effect against the progression of HIV infection, with a 58% lower risk of developing AIDS in the first 4 years after seroconversion and a 19% lower risk during the next 4 years of observation after seroconversion." (PMID 35407496, 2022). "In a study of over 3000 HIV-positive people, those who had one mutant CCR2 gene developed AIDS two to four years later than people who had two normal copies of the CCR2 gene." (PMID 26300579, 2015). "Studies have also shown that homozygosity for this mutation is associated with a delayed progression to disease, while individuals who are heterozygous for CCR2-64I progress quickly to AIDS." (PMID 26300579, 2015). "Many populations studies conducted worldwide have been shown that genetic variants CCR5-Δ32 (32-bp deletion), CCR2-64I (V → I) and SDF1-3′A (G-801A) slower the rate of HIV-1 progression thus leading to delayed onset and reduced severity of AIDS." (PMID 26322257, 2015). "CCR2-64I and SDF1-3′A mutant alleles are also shown to be associated with suppression of HIV-1 progression to AIDS; however, the suppressive effect is lower in comparison to CCR5-Δ32." (PMID 26322257, 2015). "These chemokine receptors were more known to act as co-receptors for HIV entry into the leukocytes, as CCR5∆32 and CCR2-V64I have shown to create high resistance against AIDS progression." (PMID 23493039, 2012). "This haplotype has been associated with faster progression to AIDS in individuals carrying the wild type coding region for CCR5 and CCR2, and homozygous for CCR5P1." (PMID 17651505, 2007). "CCR5 and CCR2 gene polymorphisms (SNPs) have been associated with protection against HIV transmission in adults and with delayed progression to AIDS." (PMID 17786209, 2007). "The CCR5 polymorphism results in the absence of cell surface CCR5 expression, whereas the CCR2-64I gene variant confers resistance to AIDS progression, probably due to the ability of this mutant receptor to heterodimerize with the CCR5 and CXCR4 receptors." (PMID 39346778, 2024). "This signal transduction pathway is required for expression of CCL2, a chemokine playing an important role in AIDS pathogenesis by recruiting CCR2 positive cells as new targets for infection, contributing to immune activation and enhancing viral replication both in macrophages and T lymphocytes." (PMID 23555755, 2013).
AIDS (continued). "In addition to the known CCR5 and CCR2 associations, significant associations were identified for CCR3, CCR8, and CCRL2 on progression to AIDS." (PMID 22046140, 2011). "CCR2-V64I polymorphism has been previously reported to influence the progression to cervical cancer in some populations and has also been associated with decreased progression from HIV infection to AIDS." (PMID 20537184, 2010). "Also, CCR2 is indispensable for macrophage-dependent inflammatory reactions and regulates monocyte and macrophage recruitment, and has been correlated with delayed AIDS progression in HIV infection." (PMID 40241721, 2025). "In a combination of five AIDS cohorts constituting a total of 3003 patients, CCR2V64I was associated with 2–4 years postponement of AIDS relative to homozygotes for the other allele; however, disease delay was not linked to CCR2 genotype in the ALIVE cohort, which consisted of 94% African Americans." (PMID 30534128, 2018). "About 30% of long-term survivors who had been infected with HIV for at least 16 years or more without developing AIDS had at least one CCR2 or CCR5 mutant gene." (PMID 26300579, 2015). "Heterozygous individuals for CCR2-64I progress slower to AIDS, although no clear effect in protecting against HIV-1 infection has been documented." (PMID 17651505, 2007). "However, the study does not present data on the relationship of these CCR2-64I and SDF1-3 A mutations with mortality, clinical profile or distribution of defence cells, or other important biological functions that define AIDS." (PMID 40413451, 2025). "In HIV-1/AIDS, the mutation of valine (V) to isoleucine (I) in CCR2 has not been shown to affect susceptibility to infection, but HIV-infected persons, heterozygous or homozygous for this mutation appeared to progress to AIDS or death more slowly." (PMID 23880174, 2013).
autoimmune disease (22 papers, 2006 to 2025). A disorder resulting from loss of function or tissue destruction of an organ or multiple organs, arising from humoral or cellular immune responses of the individual to their own tissue constituents. "The CCRs genes CCR5 and CCR2 have been associated withcarcinogenesis and angiogenesis, inflammatory disorders, and autoimmune diseases." (PMID 26982176, 2016). "CCR2 deficiency also reduces Th1 response and the severity of experimental autoimmune diseases." (PMID 34804061, 2021). "Recent studies have revealed the important role of C-C chemokine receptor type 2-positive (CCR2+) macrophages in autoimmune diseases and tissue fibrosis, and suggest that they are critical for valve remodeling in RHD." (PMID 40276383, 2025). "Chemokine (C–C motif) receptor 2 (CCR2) is involved in important physiological and pathological processes, such as inflammation and autoimmune diseases." (PMID 35725391, 2022). "It is worth investigating the effect of CCR2 in autoimmune diseases, so as to identify potential therapeutic targets." (PMID 35875970, 2022). "Conclusively, targeting the CCL2/CCR2 axis is considered to be an attractive target for the treatment of autoimmune diseases and viral infections." (PMID 35702353, 2022). "Despite this, CCR2 antagonism as a treatment for autoimmune diseases has been met with the disappointing results." (PMID 34804061, 2021). "CCR2 is predominantly expressed by monocytes/macrophages with strong proinflammatory functions, prompting the development of CCR2 antagonists to dampen unwanted immune responses in inflammatory and autoimmune diseases." (PMID 34804061, 2021). "Further, CCR2 antagonism has been found to exacerbate autoimmune diseases, suggesting an opposite immune regulatory role for CCR2, although the basis of anti-inflammatory role of CCR2 remains undefined." (PMID 34804061, 2021). "CCR2 antagonism has been investigated as a therapeutic for autoimmune diseases and more recently for cancer over many decades." (PMID 34804061, 2021). "Additionally, in autoimmune diseases, CCR2 inhibitors effectively reduce inflammation, demonstrating their potential as therapeutic agents." (PMID 39014433, 2024). "The relationship between the CCL2/CCR2 signaling axis and the pathogenesis of autoimmune diseases has also been widely investigated, and a common pathological feature of these autoimmune diseases is the upregulation of CCL2 and/or CCR2 expression in the lesions." (PMID 35702353, 2022). "Most of the studies focus on the role of CCR2 in inflammatory and autoimmune diseases." (PMID 24453913, 2013). "Moreover, the importance of the CCL2/CCR2 axis in recruiting inflammatory monocytes to sites that may activate a regulatory phenotype in these cells indicates the importance of polymorphisms in this axis that could impact on susceptibility to autoimmune disease." (PMID 22912822, 2012). "In autoimmune disease, expansion of the CD146-enriched IL-17+ T cell population has been reported, while no or very low correlation between IL-17 and CCR6, CD161, or CCR2 was found." (PMID 30912766, 2019). "The regulation of CCR2 on B cells in the pathogenesis of SLE needs further study, finding targeted drugs from corresponding signalling pathways deserves to take a place in the treatment of autoimmune diseases." (PMID 35875970, 2022). "The interaction between CCR2 and BCR may contribute to exploring the mechanism of autoimmune diseases." (PMID 35875970, 2022).
colon carcinoma (22 papers, 2011 to 2025). "To dissect the contribution of the CCR1- and CCR2-signaling pathways to monocyte/macrophage recruitment, we used lung and colon tumor models in Ccr1- and Ccr2-deficient mice in combination with adoptive transfer of monocytic cells during the early phase of metastasis." (PMID 39566333, 2025). "Finally, CCR2 gene expression was significantly (p < 0.001) downregulated (Log2 fold change = -0.706) in colon cancer." (PMID 35560039, 2022). "Moreover, colon cancer cell-derived CCL2 activates CCR2 on endothelial cells, thereby enabling efficient cancer cell extravasation." (PMID 31501414, 2019). "In addition, the activation of the STING/IFN-I pathway was also indicated to elevate CCR2 expression, and suppressive inflammation in colon tumors through recruiting MDSCs, CCR2 blockage-mitigated MDSC infiltration, and immunosuppression initiated by STING activation enhanced oncotherapy." (PMID 35265630, 2021). "The authors found that the compounds of LWDHW may play an important role in esophagitis and colon cancer by regulating the expression of C-C chemokine receptor 2 (CCR2), estrogen receptor 1 (ESR1), peroxisome proliferator-activated receptor gamma (PPARG), and retinoic acid receptor alpha (RARA)." (PMID 30846939, 2019). "Recent research has shown that in colon cancer, CCL2 influences the behavior of immune cells in the tumor microenvironment through its interaction with its primary receptor CCR2." (PMID 38791448, 2024). "Mechanism investigations indicated that SARI down‐regulates p‐STAT1 and STAT1 expression in colon cancer cells, following inhibition of MCP‐1/CCR2 axis activation during CAC development." (PMID 31578820, 2020). "Although MC38 colon cancer cells release high levels of CCL2 and recruit MAMs via a CCR2-dependent manner to the liver, these cells produce CCL20 and recruit TAMs via a CCR6-dependent mechanism to primary tumors established by subcutaneous injection." (PMID 30483271, 2018). "Heterogeneity of TAM phenotype was described in different tumour types and at different locations of the same tumour e.g. in colon cancer patients, CD80+, CD86+ and HLA-DR+, as well as CD163+, CD86+, CCR2+ cells were described." (PMID 26838097, 2016). "In addition, CCR2—the most common receptor for CCL2 —promotes stabilization and translocation of β-catenin via AKT/GSK3β signaling in colon cancer cells." (PMID 35562953, 2022). "The redistribution of CCR2+ and CD163+ monocytes between non-classical subpopulations was found in patients after treatment onset: NAC (for rectal cancer patients) and surgical resection (for rectal and colon cancer patients)." (PMID 36733385, 2022).
glioblastoma (22 papers, 2015 to 2025). The most malignant astrocytic tumor (WHO grade IV). "Altogether, we found a remarkable expression of CCR2 in tumor-associated macrophages in human and murine glioblastomas." (PMID 32668709, 2020). "Recent studies using murine models of glioblastoma demonstrated that increased infiltration of CCR2-positive inflammatory monocytes is associated with decreased survival time of tumour-bearing mice." (PMID 31160587, 2019). "CCR2 is also expressed by MDSCs which are strongly associated with poor outcomes in glioblastoma." (PMID 30333482, 2018). "In the future, we seek to obtain this data, re-estimate the efficacy and decay of anti-PD-1 γ1,d1 and CCR2 antagonist γ2,d2 in glioblastoma, and predict accurate doses and frequencies." (PMID 39185154, 2024). "CCR2+ MDSCs are found within the tumor microenvironment of glioblastomas, making CCR2 inhibition a desirable therapeutic mechanism for exploration." (PMID 39307417, 2024). "M2-polarized microglia suppressed phagocytosis and promoted the growth of the irradiated glioblastoma cells by CCL2/CCR2 axis." (PMID 36058942, 2022). "In mice bearing anti-PD1-resistant glioblastoma, the CCR2 antagonist CCX872 enhanced the efficacy of anti-PD1 via a reduction in MDSCs and a concomitant increase in functional T cells within the tumours, significantly improving the overall survival of mice." (PMID 33803414, 2021). "The CCL2/CCR2/CCR4 pathway exerts immunomodulatory effects on glioblastoma through the recruitment of CCR2+ GAMs, CCR2+ MDSCs and CCR4+ Tregs, and these immunosuppressive cells can contribute to immune escape by attenuating the effector T cell response." (PMID 33803414, 2021). "In the context of glioblastoma, one study reported that CCR2+ Lin- hematopoietic stem and progenitor cells (HSC) can differentiate into cross-presenting DC within mouse glioblastoma tumors." (PMID 32014107, 2020). "For example, a mouse model of glioblastoma has shown that adoptively transferred CCR2+ monocytes are recruited to the tumor and differentiate into TAMs, accounting for 85% of the total macrophage population in the tumor." (PMID 30483271, 2018). "We found that combinatorial CCR2+HSCs plus anti-PD-1 leads to increased median survival and long-term survivors in preclinical brain tumor models (glioblastoma and medulloblastoma) that are completely refractory to PD-1 treatment alone." (PMID 30333482, 2018). "We identified a six gene cytokine-related signature (CCL2, CCR2, CXCL10, IL10RB, IL17B, and IL17R) capable of dividing glioblastoma patients into a low risk score group with favorable survival and a high risk score group with poor survival." (PMID 25978454, 2015). "We previously reported that the CCL-2/CCR2 axis was involved in the biopsy-induced recruitment of inflammatory monocytes to GL261 glioblastoma as CCL-2 antibodies could be used to block their recruitment." (PMID 35883641, 2022). "We also observed high levels of CCL2 in supernatants from dissociated glioblastoma biopsies and GNS cells, inferring that CCL2 could recruit T cells through CCR2 or CCR4 to glioblastoma." (PMID 35464424, 2022). "The CCR2/CCR4-CCL2 axis has been identified in previous in vitro glioblastoma studies." (PMID 35464424, 2022). "Of note, in a mouse model of glioblastoma, CX3CR1 deficiency led to increased CNS infiltration of CCR2+ monocytes into the tumor tissue, and it was suggested that this could be linked to increased microglial IL-1β, which in turn could induce CCL2 by tumor cells." (PMID 28320442, 2017). "We extend a treatment-free glioblastoma-immune dynamics ODE model to include interventions with anti-PD-1 and the CCR2 antagonist." (PMID 39185154, 2024). "Overall, CCR5 and CXCR4 show the most prominent expression on CD8+ T-cell subsets in glioblastoma tissues, with CCR2, CXCR3 and CXCR6 displaying subset-specific glioblastoma enrichment in Tcm, Tem, and Tcm and Temra populations respectively." (PMID 35464424, 2022).
glioblastoma (continued). "In some experimental glioblastoma models, tumor cells released CCL2 to attract macrophages, and CCL2/CCR2 blockade prolonged mouse survival." (PMID 35600367, 2022). "Similar to CD4+ T cells, there was enrichment of CCR2+CD8+ Tcm cells in glioblastoma compared to paired blood samples, and approximately 50% of CD8+ glioblastoma Trms expressed CCR2." (PMID 35464424, 2022). "Quantitative analysis of chemokine receptor expression revealed a significant increase in the proportion of CCR2+CD4+ Tcm and Treg cells in glioblastoma compared to blood samples from the same patients." (PMID 35464424, 2022). "Collectively, these studies highlight a key role for the CCL2 ligand and both of its receptors (CCR2 and CCR4) in promoting the recruitment of immunosuppressive myeloid and Treg populations to glioblastoma." (PMID 33803414, 2021). "By generating medulloblastoma in Ccr2+/RFPCx3cr1+/GFP double knock-in mice we verified that, similar to glioblastoma, TAMs are a mixed population composed of BM-derived monocytes and macrophages (75%) and resident brain microglia (20%)." (PMID 31160587, 2019). "Subsequently, chemokine receptors and integrins were validated at the protein level to reveal enrichment of receptors CCR2, CCR5, CXCR3, CXCR4, CXCR6, CD49a, and CD49d in glioblastoma-infiltrating T-cell populations relative to T cells in matched patient peripheral blood." (PMID 35464424, 2022). "Having identified that CCR2+, CCR5+, CXCR3+, CXCR4+, and CXCR6+ T-cell subsets were enriched in glioblastoma, we subsequently validated the expression of complementary chemokines in dissociated glioblastoma biopsies and patient-derived glioblastoma cell-lines." (PMID 35464424, 2022). "Together, our flow cytometry analysis demonstrates that CCR5 and CXCR6 are expressed by large proportions of all glioblastoma-infiltrating CD4+ T-cell subsets, whereas CCR2 and CXCR3 enrichment was only observed in glioblastoma-infiltrating CD4+ Tcm and Tregs, and Tem and Tregs respectively." (PMID 35464424, 2022). "Similarly, in several experimental glioblastoma models, tumor cells released CCL2 to attract macrophages, and the blockade of CCL2/CCR2 prolonged mouse survival in GBM models." (PMID 36230833, 2022). "Representative histograms for CD4+ T-cell subsets illustrate the typical chemokine receptor expression patterns observed, and demonstrate that staining for CCR2, CCR5, CXCR3 and CXCR6 was robust in glioblastoma-infiltrating T-cell populations compared to matched blood naïve CD4+ T cells." (PMID 35464424, 2022). "Further analysis revealed that macrophages expressing high levels of NT5E are characterized by elevated expression of chemokines and chemokine receptors such as CCR5, CCR2, ITGAV/ITGB5, and CSF1R, which may play a role in the recruitment of macrophages into the glioblastoma microenvironment." (PMID 40191733, 2025). "Moreover, glioblastoma cells can produce kynurenine that activates AHR in TAMs; AHR recruits TAMs through CCR2/CCL2, drives the expression of the ectonucleotidase CD39 in TAMs, and plays a synergistic role with CD73 to promote adenosine production, leading to CD8+ T-cell dysfunction." (PMID 36466873, 2022). "Thus, our findings now suggest that high CCL2 abundance identified by multiple glioblastoma studies may mediate trafficking to glioblastoma through CCR2 rather than CCR4." (PMID 35464424, 2022). "However, here we show that T cells are more likely to be recruited via CCR2 than CCR4 given that both CCR2+ Tregs, and CCR2+ Tcm cells were enriched in glioblastoma tissues, and we found no enrichment of CCR4+ T cells in glioblastoma." (PMID 35464424, 2022).